CDKN2A (cyclin dependent kinase inhibitor 2A)
Diseases named in the same sentence as CDKN2A in open-access papers (continued):
Sharing a sentence is not in itself a finding about the gene and the disease.
insulinoma (4 papers, 2017 to 2024). "Loss of the tumor suppressor CDKN2A has been reported once before in a malignant insulinoma and was recently described as a marker of malignant behavior in non-functional PanNET." (PMID 32103422, 2020). "We determined protein expression of ARX and PDX1 together with ATRX, DAXX, ARID1A, and H3K36me3 by immunohistochemistry, as well as ALT and CDKN2A deletions by fluorescence in situ hybridization (FISH), in a cohort of clinically defined sporadic insulinomas." (PMID 32103422, 2020). "Insulin, glucagon, ARID1A, H3K36me3 IHC, and CDKN2A FISH were only tested on 31 cases, as for the last four insulinoma cases, no unstained TMA slides were available." (PMID 32103422, 2020). "All three primary insulinomas that metastasized showed ARX expression, 2/3 showed ALT, and 1/3 had a homozygous deletion of CDKN2A as opposed to absence of ARX expression, ALT, or CDKN2A deletions in the 32 non-metastatic cases." (PMID 32103422, 2020).
laryngeal tumors (4 papers, 2017 to 2023).
lymphoid leukemia (4 papers, 2010 to 2022). A malignant lymphocytic neoplasm of B-cell or T-cell lineage involving primarily the bone marrow and the peripheral blood. "The reduced proliferation of Vav3-deficient lymphoid leukemia B-cell progenitors is associated with increased expression of at least Cdkn2a and Cdkn2b, genes known to be regulated by PRC." (PMID 35650206, 2022). "Similarly, CDKN2A loss was linked to RAG activity in lymphoid leukemia." (PMID 20082691, 2010). "However, Rag1−/− mice with concomitant deletion of the tumor suppressor locus Cdkn2a also develop lymphoid leukemias, implying that mechanisms of lymphoid leukemia development are not entirely dependent on mistargeted V(D)J recombination." (PMID 23487523, 2012).
myelodysplastic syndrome (4 papers, 2021 to 2023). A clonal hematopoietic disorder characterized by dysplasia and ineffective hematopoiesis in one or more of the hematopoietic cell lines. "Methylation changes in the 9p21 chromosomal regions consisting of the cyclin-dependent kinase inhibitor 2B (CDKN2B) and cyclin-dependent kinase inhibitor 2A (CDKN2A) genes have been frequently associated with myelodysplastic syndromes and AML." (PMID 34358067, 2021). "Thus, we demonstrate that constitutive activation of IL7RA can initiate preleukemia in primary human hematopoietic progenitors and cooperates with CDKN2A silencing in progression into BCP-ALL." (PMID 35115489, 2022).
myeloid leukemia (4 papers, 2019 to 2024). A clonal proliferation of myeloid cells and their precursors in the bone marrow, peripheral blood, and spleen. "Moreover, the protein complex formed by HOXA9 and C/EBPα targeted Cdkn2a/b to overcome G1 phase blockage, promoted the proliferation of bone marrow cells and advanced the process of myeloid leukemia." (PMID 38605318, 2024).
neuroendocrine carcinoma (4 papers, 2015 to 2023). A malignant neuroendocrine neoplasm composed of cells containing secretory granules that stain positive for NSE and chromogranin. "Mutations in CDKN2A or RB1 co-occurring with SMARCA4 or ARID1A have been reported previously in olfactory neuroblastoma and neuroendocrine carcinoma." (PMID 38201285, 2023).
neurofibromatosis (4 papers, 2018 to 2023). A hereditary neoplastic syndrome in which tumors grow in the nervous system. "Peripheral nerve sheath tumors (PNSTs) may arise sporadically or in the presence of genetic disorders, including neurofibromatosis (NF) types 1 and 2, schwannomatosis, and in patients with large genetic deletions involving the CDKN2A gene." (PMID 29946502, 2018).
neurofibromatosis type 1 (4 papers, 2020 to 2024). A clinically heterogeneous, neurocutaneous genetic disorder characterized by cafe-au-lait spots, iris Lisch nodules, axillary and inguinal freckling, and multiple neurofibromas. "No specific physical findings, such as skin fibromas and café-au-lait spots in neurofibromatosis type 1, have been reported in CDKN2A variant carriers." (PMID 38961426, 2024). "Notably, somatic changes in NF1, CDKN2A/B, and PRC2 are found in most MPNST regardless of their etiology (e.g. neurofibromatosis type 1-associated vs. sporadic vs. radiation-induced), indicating that similar molecular mechanisms impact pathogenesis in these neoplasms." (PMID 32642732, 2020).
pulmonary arterial hypertension (4 papers, 2022 to 2025). Pulmonary arterial hypertension (PAH) is a group of diseases characterized by mean pulmonary artery pressure >20 mmHg and elevated pulmonary arterial resistance leading to right heart failure. "A transcriptomic study employing clinical samples from patients with pulmonary arterial hypertension (PAH) identified primary glycolysis genes (CASP3, IGF1, CDKN2A, and KARS) associated with PAH through combined analysis of scRNA-seq and bulk transcriptomic data." (PMID 41516041, 2025).
schwannoma (4 papers, 2013 to 2023). A benign, usually encapsulated slow growing tumor composed of Schwann cells. "To investigate this duplication in schwannomatosis, we screened the coding sequence of CDKN2A in one schwannoma sample from this same patient." (PMID 35723634, 2022). "However, many patients and families with schwannomatosis do not have identifiable germline variants in NF2, SMARCB1, LZTR1, CDKN2A, or DGCR8, and efforts have been underway to identify other responsible molecular drivers of schwannoma predisposition." (PMID 37821623, 2023). "Previous analysis of schwannoma DNA identified LOH on chromosome 22, but subsequent MLPA analysis for CDKN2A failed for this sample." (PMID 35723634, 2022).
somatotroph adenomas (4 papers, 2021 to 2026). "Germline genetic testing revealed a pathogenic variant in AIP gene in 2 patients with growth hormone excess (GHE) and a likely pathogenic variant in CDKN2A in a patient with Cushing’s disease (CD)." (PMID 40813536, 2025). "Somatotroph adenomas from patients with or without AIP mutation abundantly express GDNF, but AIP-mutated tissues have less CDKN2A-ARF expression." (PMID 34588620, 2021).
testicular cancer (4 papers, 2018 to 2025). A primary or metastatic malignant neoplasm that affects the testis. "Testicular cancer survivors (TCS) exposed to chemotherapy have an increased expression of CDKN2A/p16INK4a and a lymphocyte phenotype associated with immunosenescence." (PMID 39300957, 2024). "CDKN2A showed a positive correlation in stomach, bladder, prostate, and liver; negative in rectal, cervical, kidney‐clear cell, thyroid, and testicular cancers." (PMID 40548474, 2025).
thyroid tumours (4 papers, 2006 to 2023). "Nevertheless, high CDKN2A mRNA levels were also found in some profiles H and L thyroid tumors (associated with CDK4 phosphorylation)." (PMID 37964967, 2023).
tumor predisposition syndrome (4 papers, 2017 to 2025). "Clinicians and genetic professionals should be cognizant of this expanded range of phenotypes and consider CDKN2A as a candidate gene for tumor predisposition syndrome in individuals and families presenting with such broad spectrum of cancers." (PMID 33766116, 2021). "Familial melanoma-astrocytoma syndrome is a tumor predisposition syndrome caused by inactivating germline alteration of the CDKN2A tumor suppressor gene on chromosome 9p21." (PMID 28699883, 2017).
vitiligo (4 papers, 2020 to 2025). Generalized well circumscribed patches of leukoderma that are generally distributed over symmetric body locations and is due to autoimmune destruction of melanocytes. "Among the upregulated RBP genes, CDKN2A is involved in regulating the melanocyte cycle, and HLA-A2 gene frequency is increased in patients with vitiligo." (PMID 38438962, 2024).
alcohol abuse (3 papers, 2015 to 2024). The use of alcoholic beverages to excess, either on individual occasions ("binge drinking") or as a regular practice. "The derogation of the WNT-CTNNB1-STK11 and CDKN2A-HGF-MET pathway can constitute the carcinogenesis in young patients with SCCT where a longstanding nicotine or alcohol abuse is missing." (PMID 25633809, 2015).
B-cell acute lymphoblastic leukemia (3 papers, 2015 to 2023). A neoplasm of lymphoblasts committed to the B-cell lineage, typically composed of small to medium-sized blast cells. "Additionally, B-cell acute lymphoblastic leukemia patients with CDKN2A/2B deletions exhibited poor 2 year OS and relapse-free survival rates." (PMID 37483430, 2023).
brain glioma (3 papers, 2020 to 2025). A malignant glioma that involves the brain. "EGFR has been shown to initiate brain gliomas with short latency in mice only when combined with multiple tumor suppressor losses, such as Cdkn2a and Pten." (PMID 32727536, 2020).
central nervous system lymphomas (3 papers, 2024 to 2025). "Recurrent mutations in the JAK–STAT, NF-κB, and B-cell receptor (BCR) pathways, including CD79B, MYD88, and CDKN2A deletions, have been identified as the defining characteristics of primary central nervous system lymphomas." (PMID 40538656, 2025).
colorectal adenoma (3 papers, 2019 to 2025). An adenoma that arises from the colon or rectum. "For example, the methylation of the CDKN2A gene, a well-documented event in colorectal adenomas, was confirmed in our dataset." (PMID 40002249, 2025).
diffuse midline glioma (3 papers, 2022 to 2025). A diffuse glioma that arises from the midline structures of the central nervous system. "CDKN2A is a cell cycle regulator that mediates progression of the cell cycle past the G1 checkpoint and is frequently deleted or silenced via methylation in cancer, including diffuse midline glioma (DMG), where it has been shown in murine models to be downregulated by the K27M mutation." (PMID 41408661, 2025).
dyslipidemia (3 papers, 2014 to 2023). "The area under ROC curve for the prediction model of prediabetes on the predictors including residence, waist-hip ratio, and systolic blood pressure, dyslipidemia and CDKN2A-rs10811661 polymorphism was 0.646 (95 % CI: 0.614 − 0.677, P < 0.0001)." (PMID 26334876, 2015). "The study suggested that the CDKN2A-rs10811661 polymorphism, waist-hip ratio, systolic blood pressure, and dyslipidemia were significantly associated with the increased risk of prediabetes in a Vietnamese population." (PMID 26334876, 2015). "Our data reveal a previously unknown function of Cdkn2a in beige fat biology and suggest that inhibitors of the Cdkn2a pathway would be beneficial in reversing the deleterious effects of metabolic syndromes." (PMID 37169793, 2023).
endometrial stromal sarcoma (3 papers, 2017 to 2023). "Consistent with this cellular infection spectrum, we show that intra-uterine injection of ecotropic MuLE viruses expressing oncogenic HrasG12V together with knockdown of Cdkn2a induce high-grade endometrial stromal sarcomas." (PMID 28982163, 2017).
hepatoblastoma (3 papers, 2023 to 2024). Hepatoblastoma (HB) is a malignant hepatic tumor and is the most common pediatric liver cancer. "One of the major epigenetic alterations observed in hepatoblastoma (HB) is the hypermethylation of tumor suppressor genes, such as RASSF1A and CDKN2A, which contributes to their silencing." (PMID 39596558, 2024).
kidney injuries (3 papers, 2020 to 2021). "In another study, an elevation in the expression of the p16INK4A transcript, a product of the CDKN2A gene, was reported in acute kidney injury in young mice." (PMID 33981746, 2021).
liver angiosarcoma (3 papers, 2013 to 2024). A malignant vascular neoplasm arising from the liver. "Studies of liver angiosarcoma showed that p16INK4a was repressed by promoter methylation in 63% (12 out of 19) of tumor samples, whereas 5% (1 out of 19) exhibited homozygous deletion and 10% (2 of 19) exhibited loss of heterozygosity at the CDKN2A locus." (PMID 24046386, 2013). "This has shown that most sporadic liver angiosarcoma cases have hypermethylation of the CDKN2A (p16INK4A) promoter." (PMID 38826780, 2024). "In other reports, a primary skin angiosarcoma and liver angiosarcoma lacked expression of p16, the product of the Cyclin Dependent Kinase Inhibitor 2A (CDKN2A) gene." (PMID 28056866, 2017).
low grade glioma (3 papers, 2016 to 2023). A grade I or grade II glioma arising from the central nervous system. "For example, in paediatric low-grade gliomas (pLGG), acquisition of CDKN2A deletion at relapse may define a higher risk subgroup and may potentially be targetable." (PMID 36467471, 2022).
lymphoid tumor (3 papers, 2011 to 2019). "dup(1q)/gain of CKS1B, del(6q)/deletion of MYB, and del(9p)/deletion of CDKN2A, which are common in lymphoid neoplasms, were detected at a low frequency in adult B‐ALL patients with hyperdiploidy." (PMID 31173486, 2019). "It is not clear if CDKN2A is mutated in our mouse tumors, although we have preliminary evidence that expression of at least the INK4A is decreased in a subset of the lymphoid tumors (Resar, unpublished data)." (PMID 22053823, 2011).
mantle cell lymphoma (3 papers, 2006 to 2022). Mantle cell lymphoma is a rare form of malignant non-Hodgkin lymphoma affecting B lymphocytes in the lymph nodes in a region called the ``mantle zone''.
melanocytic nevus (3 papers, 2017 to 2021). A neoplasm composed of melanocytes that usually appears as a dark spot on the skin. "Setting aside the permanence of OIS, melanocytic nevus arrest was largely thought to be driven by induction of p16INK4A expression from the CDKN2A gene." (PMID 34812139, 2021). "In this context, it is also interesting to note that melanocytic naevi with mutations in the NRAS signalling pathway (NRAS or BRAF mutations) require additional driver mutations to avoid senescence, e.g., in the CDKN2A locus." (PMID 33138083, 2020).
mucosal melanoma (3 papers, 2015 to 2024). A melanoma that arises from a mucosal site. "At present, some studies have found that mutations that activate SF3B1 and KIT, the deletion of CDKN2A, PTEN, or SPRED1, and the amplification of CDK4, TERT, KIT, MDM2, or CCND1 are common in mucosal melanoma." (PMID 38065883, 2023).
Nephroblastoma (3 papers, 2004 to 2025). An embryonal neoplasm characterized by the presence of epithelial, mesenchymal, and blastema components. "Although p16INK4a(CDKN2a) promoter methylation has been reported in advanced stage Wilms' tumours, this trend was not significant in our series, and to date no specific clinicopathological features have been associated with SLIT2, CASP8 and RASSF1A methylation." (PMID 14735202, 2004).
oligodendroglial tumor (3 papers, 2006 to 2024). Oligodendrogliomas are cerebral tumors that are differentiated from other gliomas on the basis of their unique genetic characteristics and better response to chemotherapy. "Upregulation of angiogenesis factors and a variety of genetic alterations including deletion of CDKN2A, loss of chromosome 10, downregulation of ATase and cyclooxygenase-2 expression have been associated with progression and poor prognosis in oligodendroglial neoplasms." (PMID 17031404, 2006). "Therefore, CDKN2A/B HD can be used as a molecular aid in oligodendroglial tumors that are difficult to grade." (PMID 38109891, 2024). "Therefore, based on these results, it might be useful to determine CDKN2A HD status in oligodendroglial tumors with difficulty in grading." (PMID 38109891, 2024). "The genes found to be most frequently methylated in oligodendroglial tumors were RASSF1A (80.3%), CASP8 (70.5%), and CDKN2A (52.5%)." (PMID 27367901, 2016). "In accordance with previous studies, high methylation rates were found for CDKN2A 17, CDKN2B 18, and RASSF1A 8, suggesting that aberrant methylation of these genes may indicate early change in tumorigenesis of oligodendroglial tumors, regardless of cell type." (PMID 27367901, 2016).
oral cavity cancer (3 papers, 2009 to 2022). A primary or metastatic malignant neoplasm involving the oral cavity. "Specifically, an independent sample t test was performed on mRNA expression data of the CDKN2A and PLAU genes between OSCC (only oral cavity cancer was selected from HNSCC) and normal tissues." (PMID 33968767, 2021).
parathyroid adenomas (3 papers, 2010 to 2023). "Our study confirms the methylation-mediated transcriptional silencing of both CDKN2A and CDKN2B, and is the first study to demonstrate that the hypermethylation of CDKN2B is almost equivalent to CDKN2A in parathyroid adenomas." (PMID 28600574, 2017). "Gene expressions of cyclin D1 (CCND1) and regulatory molecules (CDKN2A, CDKN2B and RASSF1A) was analysed in parathyroid adenoma tissues (n = 30)." (PMID 28600574, 2017). "The relative expressions of the CDKN2A, CDKN2B and RASSF1A genes were analysed by quantitative RT-PCR and were related to the cyclin D1 (CCND1) expression in parathyroid adenoma samples." (PMID 28600574, 2017). "In the present study we analysed the expression patterns of three potential tumor suppressor genes, CDKN2A, CDKN2B and RASSF1A, in sporadic parathyroid adenomas." (PMID 28600574, 2017). "In this study we found that the promoter region of the three genes (CDKN2A, CDKN2B and RASSF1A) examined in sporadic parathyroid adenomas is frequently hypermethylated with the resultant reduced expression of their respective gene products." (PMID 28600574, 2017). "In conclusion, reduced expression of CDKN2A, CDKN2B and RASSF1A with significant hypermethylation of promoter region of these genes and inactivation of these genes through epigenetic regulation may be important factor in tumorigenesis in substantial proportion of parathyroid adenomas." (PMID 28600574, 2017).
parathyroid tumors (3 papers, 2010 to 2022). "Other specific genes whose pathways are linked to the development of parathyroid tumors, such as RIZ1, APC, RASSF1A, CDKN2A/p16, CDKN2B/p15, RB1, WT1, GATA4, PYCARD, SFRP1 and SFRP2, also appeared to be hypermethylated in both malignant and benign parathyroid tumors." (PMID 35628190, 2022). "Also, our study shows that the transcriptional silencing of CDKN2A and CDKN2B due to hypermethylation in at least 50% of sporadic parathyroid tumors." (PMID 28600574, 2017).
sarcomatoid carcinoma (3 papers, 2004 to 2019). A malignant epithelial neoplasm characterized by the presence of spindle cells and anaplastic morphologic features.
serous carcinomas (3 papers, 2018 to 2021). "Postulated sensitivity to CDK4/6 inhibitor therapy was mostly due to CCND1 gain – particularly in patients with high-grade serous carcinomas- and CDKN2A loss." (PMID 33947352, 2021).
tauopathy (3 papers, 2022 to 2025). Neurodegenerative disorders involving deposition of abnormal tau protein isoforms (tau proteins) in neurons and glial cells in the brain. "Removal of the p16Ink4a-positive senescent cells, for instance, using a suicide gene under the regulation of the Cdkn2a promoter has been shown to attenuate progression of age-related decline and preserve cognitive function in both an accelerated aging AD mouse model and a tauopathy mouse model." (PMID 35311644, 2022).